KL (klotho)
Diseases named in the same sentence as KL in open-access papers (continued):
Sharing a sentence is not in itself a finding about the gene and the disease.
cardiac hypertrophy (continued). "As MI is recognized as an important cause of cardiac hypertrophy and remodelling development, the compensative expression of Klotho after cardiac injury could protect against left ventricular hypertrophy (LVH) or additional heart failures." (PMID 32319182, 2020). "Particularly, it provides evidence that CKD-associated cardiac hypertrophy correlates with reduced eGFR and soluble Klotho and Vitamin D levels, and is indicative of a generalized pro-inflammatory status, as evidenced by increased levels of IL-6, ACR, PTH, P and FGF23." (PMID 30934737, 2019). "In CKD mice Klotho deficiency correlates with the extent of cardiac hypertrophy and fibrosis." (PMID 29849175, 2018). "For example, in diabetic mouse models such as Akita and db/db, exogenous Klotho or Klotho-derived peptides can reduce glomerular hypertrophy, fibrosis and oxidative stress, while improving myocardial hypertrophy and retinal ganglion cell damage." (PMID 41438297, 2025). "In a heterozygous Klotho gene-knockout CKD mouse model, detectable sKlotho concentrations were linked to rapid cardiac hypertrophy and fibrosis." (PMID 41141519, 2025). "In Klotho-deficient mice, ISO-induced stress exaggerated pathological cardiac hypertrophy and remodeling." (PMID 40799848, 2024). "The induction of cardiac FGF23 and reduced Klotho was strongly linked to LVH in the CKD cohort, with mice displaying more severe cardiac hypertrophy and fibrosis under conditions of higher FGF23 and lower Klotho levels." (PMID 38846254, 2024). "It is likely that the induction of cardiac hypertrophy needs a more drastic decline in klotho expression." (PMID 36674838, 2023). "Considering the role of IGF1 in cardiac disorders, the ability of Klotho to inhibit IGF in several heart hypertrophy models was investigated." (PMID 37985893, 2023). "Klotho appears to be capable of regulating intracellular calcium homeostasis and inhibiting reactive oxygen species, hence reducing myocardial hypertrophy, fibrosis, and cardiotoxicity." (PMID 35509269, 2022). "Most critically, recent studies have demonstrated that Klotho supplementation protects mice from indoxyl sulfate-induced ventricular hypertrophy." (PMID 36457804, 2022). "Klotho overexpression attenuated renal hypertrophy, albuminuria, glomerular mesangial expansion, and endothelial glycocalyx loss in the AKITA mice." (PMID 35692408, 2022). "Increasing evidence suggests that Klotho regulates intracellular Ca2+ homeostasis and inhibits reactive oxygen species levels to mitigate cardiac hypertrophy, fibrosis and cardiotoxicity." (PMID 35509269, 2022). "As a potential mechanism of these observations, FGF23 is reported to induce cardiac hypertrophy via Klotho-independent signaling through the FGFR4." (PMID 34765890, 2021). "Recently, researchers further demonstrated that hybridization of Klotho transgenic mice significantly attenuated renal hypertrophy, albuminuria, glomerular mesangial expansion, and endothelial glycocalyx loss in spontaneously diabetic Ins2Akita (AKITA) mice." (PMID 32054986, 2020). "Most importantly, recent background studies have shown that Klotho protects against cardiac hypertrophy in mice independently of FGF-23, whereas recombinant α-Klotho has been demonstrated to act therapeutically against uremic cardiomyopathy in mice." (PMID 31185930, 2019). "Klotho is involved in mechanisms of defense against the development of heart hypertrophy and remodeling, as well as the vascular calcification and atherogenesis." (PMID 30671457, 2018). "Moderate aerobic training attenuates aging-induced pathological cardiac hypertrophy at least partially by restoring the Klotho levels, attenuating oxidative stress, and reduction in the phosphorylation of ERK1/2, P38 and fibrosis." (PMID 30524691, 2018).
cardiac hypertrophy (continued). "It seems that there is no comprehensive and clear view of the exact effect of aerobic exercise on the levels of Klotho protein and its relationship with ERK1/2 and P38 phosphorylation, and their association with aging-induced cardiac hypertrophy." (PMID 30524691, 2018). "In previous experimental studies, restoration of serum klotho levels ameliorated cardiac hypertrophy and vascular calcification, and haplodeficiency of the Klotho gene caused arterial stiffness." (PMID 29506503, 2018). "First, owing to the cross-sectional nature of the study, it is hard to demonstrate the cause-effect inferences about the relationship between serum klotho levels and cardiac hypertrophy or arterial stiffness." (PMID 29506503, 2018). "The potential impact of these investigations is compensatory action of Klotho in ischemic heart to prevent cardiac hypertrophy and remodeling." (PMID 30671457, 2018). "It suggests the compensatory mechanism of Klotho to prevent the development of pathological heart hypertrophy due to the cardiac damage." (PMID 30671457, 2018). "Soluble Klotho protects the heart via inhibition of the transient receptor potential cation channel 6 (TRPC6) gene whose overexpression leads to cardiac hypertrophy and remodeling." (PMID 28977159, 2017). "Using transverse aortic constriction (TAC) in gene-targeted mouse models, we examine the role of Fgf23 and Klotho in cardiac hypertrophy and dysfunction induced by pressure overload." (PMID 28900153, 2017). "To obtain further insight into potential FGFR-mediated signalling mechanisms in TAC-induced cardiac hypertrophy, we investigated mRNA expression of Fgfr1, Fgfr3 and Fgfr4 in WT, VDRΔ/Δ, Fgf23−/−/VDRΔ/Δ, and Klotho−/−/VDRΔ/Δ mice, 4 weeks after TAC." (PMID 28900153, 2017). "In ESRD, high serum phosphate levels, high fibroblast growth factor 23 (FGF23) levels and low serum Klotho levels are considered to play a role in cardiac hypertrophy and cardiac fibrosis." (PMID 27189482, 2016). "Furthermore, recombinant Klotho administration in mice reduced infarct area and attenuated cardiac hypertrophy and fibrosis." (PMID 39815421, 2025). "This suggests that klotho deficiency is a primary contributor to cardiac hypertrophy in CKD, independent of FGF23 and phosphate." (PMID 40559238, 2025). "There are several studies dealing with Klotho and cardiac hypertrophy in the context of CKD." (PMID 38787156, 2024). "Moreover, their examination of myocardial tissue from CKD patients indicated an increase in FGFR4 expression alongside diminished levels of soluble Klotho, showing a correlation with cardiac hypertrophy." (PMID 38846254, 2024). "In addition, Ding reported that klotho inhibits angiotensin II-induced cardiac hypertrophy, fibrosis, and dysfunction in mice through suppression of the transforming growth factor-β1 signaling pathway." (PMID 36724065, 2023). "At the cardiac level, there were not any macroscopic differences indicative of cardiac hypertrophy in any group independently of AKI induction or any deficiency in klotho expression." (PMID 36674838, 2023). "Additionally, Klotho protects heart function and inhibits cardiac hypertrophy and fibrosis in patients with AKI." (PMID 35509269, 2022). "Moreover, it has been recently described that FGF23-induced cardiac hypertrophy in mice is attenuated by soluble Klotho administration." (PMID 35042527, 2022). "However, when secreted Klotho protein was added externally, myocardial hypertrophy and interstitial fibrosis were alleviated in Kl (−/−) and elderly wild-type mice, and cardiac function was improved." (PMID 35721561, 2022). "In addition, FGF23 increases renal sodium reabsorption by upregulating the Na+:Cl− cotransporter in the distal tubules via a Klotho-dependent pathway, leading to volume expansion, hypertension, and cardiac hypertrophy." (PMID 34765890, 2021). "It is reported that FGF23 induces cardiac hypertrophy by Klotho-independent binding to FGFR4." (PMID 34765890, 2021).
cardiac hypertrophy (continued). "Likewise, klotho hypomorphic mice develop severe cardiac hypertrophy and fibrosis with activation of the calcineurin/NFAT and TGF-β signaling pathways, and heterozygous klotho-deficient mice show decreased EF, SV, cardiac output, and impaired cardiac geometry." (PMID 34778257, 2021). "Considering our results, we speculate that there is a compensative production of cardiac Klotho during heart disorders to reduce the area of injury and to protect cardiac tissue from damage and further lesions, like heart hypertrophy and remodelling." (PMID 32319182, 2020). "Decreasing the expression of Klotho may increase fibroblast growth factor 23 (FGF23), and the increased FGF23 level may cause cardiac hypertrophy and CHF." (PMID 33020564, 2020). "Klotho was shown to protect against IS-induced myocardial hypertrophy in a mouse model of CKD." (PMID 32464602, 2020). "A positive correlation between FGF23 and cardiac hypertrophy exists in a Klotho-deficient state, but not in a Klotho-repleted state." (PMID 32150864, 2020). "For instance, Klotho has been shown to reduce stress-induced cardiac hypertrophy by inhibiting cardiac TRPC6 channels in cardiomyocytes, as well as to stimulate TRPV5 receptors in the renal distal tubules, thus allowing the regulation of phosphate metabolism independently of calcium levels." (PMID 30934737, 2019). "Moreover, and unlike what was observed by Tanaka and collaborators, these associations were significant in all CKD patients, particularly between Klotho and cardiac hypertrophy." (PMID 30934737, 2019). "However, clinical studies have shown mixed results with regards to serum klotho and cardiac hypertrophy." (PMID 29506503, 2018). "Intravenous delivery of a transgene encoding soluble Klotho ameliorated cardiac hypertrophy in Klotho-deficient CKD mice without changes in serum FGF23 and phosphate levels." (PMID 30200452, 2018). "Taken together, our data suggest that the well-established cardiac FGF23/FGFR4 signaling involved in the development of pathologic cardiac hypertrophy with the parallel appearance of cardiac fibrosis is induced in kl/kl mice with high FGF23 levels and klotho deficiency." (PMID 29977226, 2018). "Furthermore, klotho protects against myocardial hypertrophy by reducing indoxyl sulfate-mediated oxidative stress in vitro and in vivo." (PMID 29977226, 2018). "For this reason, oxidative stress can probably be considered as a direct or indirect (by reducing Klotho) upstream regulator of MAPKs and a possible mechanism that could potentially impact the fibrosis and cardiac hypertrophy." (PMID 30524691, 2018). "While normalization of serum FGF23 and phosphate levels by dietary phosphate restriction and blood pressure with antihypertensive drugs did not reverse cardiac hypertrophy in Klotho-deficient CKD mice." (PMID 30200452, 2018). "Neither deletion of Fgf23 protected against pressure overload-induced cardiac hypertrophy and fibrosis, nor klotho deficiency exacerbated TAC-induced pathological hypertrophic phenotype in mice." (PMID 29892269, 2018). "Recombinant klotho ameliorated CKD-associated cardiac hypertrophy without significantly altering serum phosphate and/or FGF23 levels." (PMID 29250031, 2017). "We found that neither Fgf23 nor Klotho deficiency modulates cardiac hypertrophy induced by pressure overload." (PMID 28900153, 2017). "Therefore, the role of FGF23 and Klotho in the pathophysiology of heart hypertrophy is still unclear." (PMID 28900153, 2017). "The augmented levels of Klotho post-infarction may reflect a compensatory mechanism to prevent pathological myocardial hypertrophy." (PMID 28076518, 2016). "In contrast to wild-type and VDRΔ/Δ mutant mice, rFGF23 treatment of 3-month-old Kl−/−/VDRΔ/Δ double mutant mice did not result in renal Na+ retention and heart hypertrophy, showing that the effects of FGF23 on Na+ homeostasis and heart hypertrophy are Klotho dependent, but VDR independent." (PMID 24797667, 2014).
cardiac hypertrophy (continued). "Moreover, basic research has observed that supplementing with Klotho could protect against indoxyl sulfate-mediated cardiac hypertrophy in mice and contribute to cardiac protection during ischemia/reperfusion injury in human cardiomyocytes." (PMID 39330350, 2024). "Interestingly, loss of Klotho expression in mice is linked to the development of cardiac hypertrophy, cardiac dysfunction, and a pro-arrhythmic phenotype, although Klotho is not expressed in the heart under basal conditions." (PMID 35042527, 2022). "Moreover, through anti-oxidant, anti-fibrotic, anti-apoptotic and pro-angiogenic mechanisms, early Klotho supplementation improves lung structure, attenuates vascular remodeling and reduces cardiac hypertrophy and dysfunction in rats with experimental severe BPD complicated by PH." (PMID 32704023, 2020). "Importantly, stress-induced heart hypertrophy and remodelling were impaired by means of Klotho." (PMID 33123314, 2020). "In contrast, cardiac hypertrophy and fibrosis correlated with high phosphate levels in uremic and non-uremic klotho-deficient mice, and genetically induced elevation of soluble klotho ameliorated phosphate-induced hypertrophic growth of cardiac myocytes in vivo." (PMID 29977226, 2018). "Then, Klotho downregulated IGF/PI3K-dependent calcium channels in the mouse heart, thus protected against cardiac hypertrophy and remodelling." (PMID 37985893, 2023). "CKD mice lacking klotho exhibited more severe cardiac hypertrophy after controlling for serum phosphate and FGF23 levels." (PMID 40559238, 2025). "Similarly, increased level of Klotho and inhibition of insulin/IGF1/AKT axis was related to abolished myocardial hypertrophy and fibrosis in mice." (PMID 37985893, 2023). "The assumption that klotho acts as a cardioprotective reagent is also supported by our in vitro data showing prevention of cardiac Fgf23-induced cardiac hypertrophy by sKL in NRVMs without altering high intra-cardiac Fgf23 expression and secretion." (PMID 34778257, 2021). "The research also revealed that ROS overproduction and cardiac hypertrophy arose from an activation of mitogen-activated protein kinase (MAPK) signaling pathway and phosphorylation of MAPK (p38 and ERK1/2) was significantly reduced by exogenous Klotho." (PMID 30671457, 2018). "Although we found a profound upregulation of circulating iFgf23 as well as of cardiac and bony Fgf23 transcription after TAC, our data do not support an essential role of Fgf23 or Klotho in the pathophysiology of pressure overload-induced cardiac hypertrophy." (PMID 28900153, 2017). "Neither did the absence of Fgf23 in Fgf23−/−/VDRΔ/Δ animals protect against cardiac hypertrophy, nor did deletion of Klotho lead to further exacerbation of the TAC-induced hypertrophic phenotype, relative to VDRΔ/Δ controls." (PMID 28900153, 2017). "To test the hypothesis that Fgf23 and Klotho play an essential role in the development of cardiac hypertrophy induced by increased afterload, we induced TAC in wild-type (WT), VDRΔ/Δ, Fgf23−/−/VDRΔ/Δ, and Klotho−/−/VDRΔ/Δ mice." (PMID 28900153, 2017). "Despite the profound, aldosterone-mediated increase in circulating intact Fgf23 after TAC, our data do not support an essential role of Fgf23 or Klotho in the pathophysiology of pressure overload-induced cardiac hypertrophy." (PMID 28900153, 2017). "Klotho may also reduce proteinuria by blocking the transient receptor potential cation channel (TRPC6) in podocytes, and in the heart, Klotho attenuates stress-induced cardiac hypertrophy via inhibition of TRPC6." (PMID 32188018, 2020). "Moreover, we demonstrated that FGF23 contributes to pathologic cardiac remodeling and promotes the pro-fibrotic crosstalk between cardiac myocytes and fibroblasts resulting in enhanced cardiac hypertrophy and fibrosis in the absence of klotho." (PMID 29977226, 2018).
diabetic nephropathy (59 papers, 2013 to 2026). "Numerous studies have shown that Klotho deficiency is strongly associated with the pathogenesis of diabetic kidney disease." (PMID 39859443, 2025). "The overexpression of Klotho in diabetic nephropathy (DN) reduces the damage caused by excessive glucose in human glomerular endothelial cells (HRGECs)." (PMID 39308872, 2024). "Deficiencies in klotho are implicated in various kidney dysfunctions including diabetic nephropathy (DN) related to inflammatory responses." (PMID 37261217, 2023). "Research has shown that the decrease of klotho expression is implicated in the process of diabetes nephropathy by promoting M1 polarization." (PMID 37261217, 2023). "In a prospective study including 107 patients with diabetic nephropathy, low serum Klotho levels were linked to a higher risk of cardiac hypertrophy, cardiovascular hospitalization and mortality." (PMID 36440221, 2022). "Klotho deficiency induces Wnt activation, which, in turn, is associated with podocyte injury in mice models of diabetic nephropathy and patients with diabetes." (PMID 32188018, 2020). "Furthermore, Klotho deficiency actually aggravated HG-induced ROS and MtD which eventually deteriorated diabetic nephropathy." (PMID 33162804, 2020). "In people with type 2 diabetes and early diabetic kidney disease (DKD), circulating Klotho levels are independently and inversely associated with Ao‐PWV, the gold standard measure of arterial stiffness." (PMID 39497615, 2025). "Another study found that extracellular vesicles from albumin-induced tubular epithelial cells promote M1 macrophage polarization by targeting Klotho, accelerating the progression of diabetic kidney disease." (PMID 40534860, 2025). "For instance, Astragaloside IV has been found to elevate Klotho expression, ameliorate renal function, and mitigate podocyte apoptosis and injury in mice with diabetic nephropathy." (PMID 40134808, 2025). "Previous study found that diabetic nephropathy mice has the down-regulated Klotho and up-regulated Wnt1 and β-catenin in protein and mRNA level, exasperate damage containing proteinuria, lipid disorders, and pathological hurt of kidney tissue." (PMID 39230198, 2024). "Patients with diabetic nephropathy had a mean s.Klotho of 3.7 ng/mL and median fall in GFR of 6 mL/min/1.73 m2." (PMID 39544340, 2024). "Another example is the effect of Klotho on ameliorating diabetic nephropathy, which was carried out through Nrf2 signaling activation in podocytes." (PMID 38534403, 2024). "SGLT2i treatment increased Klotho availability in type 2 diabetic patients with poorly controlled diabetes and early diabetic kidney disease, as well as in stressed tubular cells." (PMID 36829798, 2023). "In a study including patients with diabetic kidney disease, a positive correlation was found between Klotho and reduction of eGFR, and the tubular injury marker." (PMID 37560310, 2023). "With the progression of kidney disease, the expression of klotho protein in patients with diabetic nephropathy decreases, and the decrease of klotho can activate the mTOR signaling pathway and aggravate kidney damage." (PMID 35692885, 2022). "The possible explanation is that metformin regulates the mTOR pathway by upregulating klotho and protects renal tubular cells, thereby delaying renal progression in patients with diabetic nephropathy." (PMID 35692885, 2022). "Klotho protein overexpression attenuates renal hypertrophy and glomerular injury in this mouse model of diabetic nephropathy." (PMID 35692408, 2022). "Collectively, their findings supported the idea that Klotho ameliorates inflammation, although how s-Klotho predicts inflammatory status in diabetic nephropathy differed from our results." (PMID 35603960, 2022). "The following search terms were used for the title or abstract: “diabetic kidney disease”, “diabetic nephropathy”, OR “DN” in combination with “Klotho”." (PMID 35692408, 2022).